MCL1 (MCL1 apoptosis regulator, BCL2 family member)
Diseases named in the same sentence as MCL1 in open-access papers (continued):
Sharing a sentence is not in itself a finding about the gene and the disease.
tumor (continued). "MCL1 impacts metabolism via modulating the expression of hexokinase 2 (HK2) in an mTORC1-dependent manner, which ultimately contributes to the tumor-promoting effects of MCL1." (PMID 41326406, 2025). "In GBM 8401-cell xenografted mice, tetrandrine decreases the expression of c-FLIP, MCL-1, and XIAP in tumor tissues." (PMID 40286187, 2025). "Our analysis suggested LURAP1L-AS1 to act as a molecular sponge for miR-7a-5p, miR-101-3p, miR-181a-5p, and miR-27a-3p, resulting in the upregulation of EZH2, MCL1, and KRAS, among other tumor promoting." (PMID 39995981, 2025). "Future studies examining the co-expression of RPS4X, MCL1, and HAX1 in clinical tumor samples, as well as functional studies in patient-derived models, will be essential to validate the potential oncogenic role of RPS4X." (PMID 41154579, 2025). "We demonstrated that these drugs downregulate MCL1 activity via distinct mechanisms and synergize significantly with the BCLXL inhibitor, leading to enhanced anti-tumor activity with tolerable toxicity in preclinical GC models." (PMID 40075071, 2025). "Therapy resistance, not only in hematological malignancies but across various tumor types, has increasingly been attributed in part to the overexpression of anti-apoptotic Bcl-2 protein family members, particularly BCL-xL and MCL-1." (PMID 40973765, 2025). "We extended these data across multiple pediatric tumor types, showing that BCL2L1 methylation is a broad predictor of MCL1 dependency in vitro and in vivo." (PMID 39846250, 2025). "In obese EA patients, enriched pathways were dominated by extra-nuclear estrogen signaling (e.g., ESR1, ESR2, HEY2, MCL1), suggesting a strong hormonal component in TNBC tumor biology." (PMID 41009685, 2025). "We conducted an in silico analysis using databases like The Cancer Genome Atlas, Gene Expression Omnibus, and Clinical Proteomic Tumor Analysis Consortium, along with immunohistochemistry staining, to study EGFR and Mcl-1 expression in HNCs." (PMID 38888847, 2025). "When tumor cells develop resistance, they often activate other pathways such as RAS/RAF/MAPK and Apoptotic Blockade (BCL‐2/MCL‐1)." (PMID 41355397, 2025). "MCL1, one of the highest-ranking RCD.Sig genes in both datasets, are essential for cell growth, survival, and proliferation, and play a role in the tumor immune microenvironment." (PMID 38538696, 2024). "Like the patient tumour cohort, BH3 profiling of gliomaspheres revealed dual BCL-XL and MCL-1 blocks to prevent MOMP." (PMID 39572533, 2024). "The BCL-2 antiapoptotic family consists of key molecules that regulate tumor cell apoptosis, including BCL-2, BCL-xL, BCL-w, and MCL-1." (PMID 39060763, 2024). "Other studies have shown that pediatric solid tumors are more dependent on BCL-XL and MCL-1 than BCL-2, and that the dual inhibition of BCL-XL and MCL-1 provides synergistic anti-tumor activity in EWS cell line cultures." (PMID 39199601, 2024). "This class is known as a tumor suppressor and works by targeting the BCL2,MCL1, CCND1, and WNT3A genes." (PMID 38530760, 2024). "Western blot analysis showed a significant decrease in the expression levels of MCL-1, CDK4, and phosphorylated Rb in A2058 xenograft tumor of the 5 and 10 mg/kg RC48 groups compared with the vehicle groups." (PMID 38594618, 2024). "The efficacy of KS18 significantly diminished upon Mcl-1 knockdown, thereby reinforcing that KS18’s anti-tumor activity is primarily mediated by Mcl-1 suppression." (PMID 39411073, 2024). "In all cases, a high percentage of tumor cells expressed BCL2L1 and MCL1 as anti-apoptotic genes of the BCL-2 family." (PMID 39122703, 2024).
tumor (continued). "The overexpression of Mcl-1 inhibits TIS and promotes tumor growth, whereas the downregulation of Mcl-1 delays tumor growth in vivo." (PMID 37047342, 2023). "Consistent with the c-MYC/Mcl1 prevention model, the AFP immunization also prevented cMet/β-catenin-induced HCC tumor formation (A C, and D, P < 0.05)." (PMID 37040183, 2023). "Tumor growth inhibition reaching 0.5% of control treated SU-DHL-10 xenografts is achieved in vivo and MYC and MCL1 depletion as well as evidence of apoptosis activation after enitociclib treatment is demonstrated." (PMID 37882668, 2023). "Noteworthy, along with Sp1, the reactivation of the oncosuppressive miR-29b was accompanied by the down-regulation of other miR-29b canonical targets, i.e., MCL-1 and CDK6, suggesting a pleiotropic anti-tumor activity of this drug in MM cells." (PMID 37759449, 2023). "Another interesting target of FBXO45, FBXW7, is a tumour suppressor that targets specific substrates for ubiquitination and degradation, including the known driver oncogenes of aggressive PCA MYC and Mcl-1." (PMID 36980776, 2023). "CRISPR-Cas9 screening identified druggable targets that sensitized tumor cells to IFN-γ when inactivated, such as MCL1 and TBK1, highlighting potential ICB combination therapies in CRC." (PMID 36669486, 2023). "Using vector methodology, they established a SS cell line with high NOXA expression and assessed the sensitivity of the tumor cells to venetoclax-mediated cell death, since NOXA specifically binds with MCL-1 and inactivates it." (PMID 37720343, 2023). "ABT263 treatment when combined with drugs decreasing Mcl1 levels (a BCL2 family protein), decreased tumor volume in a heterotopic (subcutaneous) model of proneural GBM71,72." (PMID 36707509, 2023). "The upregulation of pro-apoptotic genes and downregulation of anti-apoptotic genes, mainly MCL1, PDK1 and BCL2, after MET and MET + LPS treatments contributed to the tumor cell death observed." (PMID 36765551, 2023). "MiR-451 inhibits NSCLC tumor cell growth and migration by targeting LKB1/AMPK and ATF2 and sensitizes NSCLC cells to cisplatin by regulating Mcl-1." (PMID 37190222, 2023). "Tumors in the various groups were histologically indistinguishable and consisted of densely packed, small basophilic-staining tumor cells, as previously reported for c-MYC/Mcl1 mice." (PMID 37040183, 2023). "MCL-1 gains occur frequently in non-small cell lung cancer (NSCLC), and its inhibition obstructs tumor progression therapeutically." (PMID 37894324, 2023). "To further assess the combined mTOR inhibition and BCL-XL degradation as a potential therapeutic strategy for BCL-XL and MCL-1 co-dependent SCLC, we first investigated the efficacy of DT2216 + AZD8055 combination using the H1048 xenograft tumor model." (PMID 36588105, 2023). "Mcl-1, MMP2, and c-Myc mRNA levels were also reduced in the xenograft tumor tissues with TRIM47 knockdown." (PMID 36288633, 2022). "The activation of JNK, either by EGFR or chemotherapy agent, stabilizes BMI1 and MCL1 protein expressions through suppressing HUWE1 expression, which then promote tumour initiation and chemo‐resistance." (PMID 35794816, 2022). "Western blot was applied to measure the mitigation of Mcl-1, PCNA, MMP-2, MMP-9, biomarkers of EMT process and the activation of caspase cascade, reflecting the influence of ID09 to tumor malignant biological behaviors in vivo." (PMID 35002504, 2022). "In 54% of patients BCL-2 was expressed in the tumor cells, while BCL-XL and BCL-W were expressed in 88 and 90% and MCL1 in 78%." (PMID 36430230, 2022). "Ultimately, they confirmed that MYC and MCL1 contribute to CSC enrichment and tumor-initiating capacity in TNBC." (PMID 36501221, 2022).
tumor (continued). "As well as the documented tumor cell-intrinsic role for MCL-1, tumor explant and co-culture experiments have also highlighted a pro-tumor function for MCL-1 within the stromal microenvironment." (PMID 35349392, 2022). "MCL1 and BCL-XL expression in tumor cells is decreased by THZ1, making tumor cells more responsive to BH3 mimics." (PMID 35945614, 2022). "Multiregional analysis across 22 tumour types revealed frequent subclonal focal amplifications in chromosomes 1q (encompassing BCL9 and MCL1), 5p (TERT), 11q (CCND1), 19q (CCNE1) and 8q (MYC)." (PMID 36289203, 2022). "Analysis of the copy number of The Cancer Genome Atlas (TCGA) tumor samples showed that USP13 and MCL-1 were upregulated in many types of tumors, especially in lung adenocarcinoma, lung squamous cell carcinoma, ovarian cancer, and cervical cancer." (PMID 36188217, 2022). "Mcl-1 is an antiapoptotic protein of the BCL-2 family, which promotes tumor progression by inhibiting apoptosis." (PMID 36457505, 2022). "In CRC, the JAK/STAT3 pathway can directly regulate tumor immune cells and upregulates the expression of oncogenic proteins, such as c-MYC, Cyclin D1, BCL2 or MCL1 to help drive tumor progression and chemoresistance." (PMID 35501324, 2022). "In PCa, the STAT protein family promotes tumor progression and mediates therapy resistance by regulating oncogene and pro-survival gene transcription (e.g., BCL2L1, MCL1, MYC, CCND1)." (PMID 35207527, 2022). "Mcl-1 and PP5 function as antiapoptotic proteins and play critical roles in controlling cell proliferation and tumor development." (PMID 35937685, 2022). "We observed that only a high dose of SCT (10 mm) induced increases of cleaved caspase‐3 and Bax expression, as well as decreases of Bcl‐2/Bax ratio and Mcl‐1 in both HCT116 and HT1299 tumor cells." (PMID 34747157, 2022). "Myeloid cell leukaemia 1 (MCL1) is a pro‐survival member of the B‐cell lymphoma 2 (BCL‐2) family of proteins, frequently overexpressed or genetically amplified in several types of tumours." (PMID 35794816, 2022). "MDM2 was also reported to mediate HUWE1 degradation and in turn regulate the abundance of Mcl1 and PP5 to contribute to tumor cell drug resistance." (PMID 35937685, 2022). "Despite the inter-tumor heterogeneity present in GBM, GSCs seem to share, as a common denominator, Bcl-xL and Mcl-1 as pivotal factors in mounting the anti-apoptotic response." (PMID 36273072, 2022). "MCL-1 is a major antiapoptotic BCL-2 family member, which plays an important role in tumor development and therapy resistance." (PMID 35604090, 2022). "Focal copy number gain of MCL1 and B3GNT2 occurred more frequently than losses across tumor types (in 95 and 81% of total cases respectively)." (PMID 35338135, 2022). "Outgrowth of MCL-1 proficient cells is likely due to incomplete deletion of MCL-1, underscoring the importance of MCL-1 in tumour growth." (PMID 35473984, 2022). "In the Mcl-1 knockdown HCT116 tumors, reintroduction of Mcl-1 5KR mutant impaired the anti-tumor effectiveness of irradiation treatment." (PMID 35301297, 2022). "Even other authors considered GSK3β as a tumor suppressor in CLL, as they showed that GSK3β inactivation by a deregulated SYK/PKCδ pathway stabilized the antiapoptotic Mcl-1 protein." (PMID 36050315, 2022). "Analyses using Huh7 tumor lysates demonstrated that there was reduced p-STAT3 and MCL1 expression following sorafenib treatment." (PMID 36232407, 2022). "Here, we revealed that EGFR signaling mediates TCTP-induced resistance of tumor cells to CTL-mediated killing and decrease of T cell infiltration into the tumor by regulating MCL-1 and CXCL10." (PMID 35440620, 2022).
tumor (continued). "The BCL2 protein family is critical to tumor cell survival, and PDAC, in particular, is strongly dependent on the anti-apoptotic protein MCL1." (PMID 35945614, 2022). "The potent reduction of anti-apoptotic protein MCL1, coupled with the activation of caspase 3 and cleavage of PARP, substantiates the observation of tumor regression." (PMID 35267421, 2022). "Among them, Mcl-1 and Bcl-2 exerted anti-apoptotic effects in HCC cells, c-Myc and VEGF showed strong pro-tumor growth effects, and TIMP-1 was involved in the regulation of HCC metastasis." (PMID 34408811, 2021). "Upregulation of MCL-1 has been shown by several studies to be a major limiting factor in the development of ABT-737 and ABT-263 resistance in tumor treatment." (PMID 33883020, 2021). "Moreover, MCL-1-specific BH3-mimetic drugs can have higher affinity for human versus mouse MCL-1 meaning that xenograft studies may show efficient BH3-mimetic engagement of MCL-1 in the human-derived tumour at a given dose, whilst insufficiently targeting MCL-1 within the tumour microenvironment." (PMID 33785871, 2021). "Early studies positively and negatively correlated response to venetoclax to Bcl-2 and Bcl-xL or Mcl-1 protein expression, respectively, and to mitochondrial priming by BH3 mimetic peptides ex vivo in tumor cells." (PMID 34885077, 2021). "When grouping B2 and B3 TH and TC according to MCL-1 and BCL-xL expression, we found a significantly decreased tumor survival in patients with high expression of both MCL-1 and BCL-xL." (PMID 34781947, 2021). "For example, co-targeting of anti-apoptotic proteins BCL-XL or MCL-1 and MEK promotes tumor regression in KRAS-mutant tumor models compared with MEK targeting alone." (PMID 34301278, 2021). "The levels of MCL-1 and BCL-XL were decreased and those of cleaved caspase-3 increased in tumor tissues following treatment with Ag-SP-DNC." (PMID 33708128, 2021). "We demonstrated that IR elicited A549 cell apoptosis and augmented PBMCs-mediated tumor cell death through prohibiting IFNγ-mediated phosphorylation of STAT1 and STAT3 and gene expression of PD-L1 and MCL1." (PMID 34685495, 2021). "To corroborate the in vitro data, we used the tumor xenografts from HFD-fed mice to clarify the expression of pSTAT3, CEBPD, and MCL1." (PMID 34156978, 2021). "miR-15a and miR-16 act as tumor suppressors: they downregulate multiple oncogenes (BCL2, MCL1, CCND1, and WNT3A), decreasing PC cell survival, proliferation, invasion, and EMT by targeting TGF-β signaling." (PMID 34830196, 2021). "The remarkable in vitro and in vivo anti-tumor activities of AZD5991 in both MM and AML models support its consideration as a strong clinical candidate in different Mcl-1 dependent hematologic malignancies." (PMID 34349655, 2021). "miR-29 is considered a tumor suppressor miRNA given its ability to repress genes involved in proliferation and cell survival, such as AKT3, DNMT3A/B, MCL1, and CDK6, and its frequent downregulation in cancer, including leukemia, ovarian, or breast." (PMID 33808771, 2021). "FBXW7 is a key substrate recognition subunit of the SCF complex that acts as a tumor suppressor gene by controlling the proteasome-mediated degradation of oncoproteins, such as c-MYC, MCL1, Notch1/4, cyclin E, and mTOR." (PMID 33676554, 2021). "Studies have also shown that USP7 participates in the stabilization of anti-apoptotic protein MCL-1, leading to the upregulation of MCL-1 levels in tumor cells." (PMID 34869041, 2021).
tumor (continued). "In this study we show another inhibitor, AZD4320 that targets BCL-XL (and BCL-2), can also potently kill MPM tumor cells in vitro (EC50 values in the 200 nM range) and this effect is enhanced by co-inhibition of MCL-1 using AZD5991." (PMID 34050131, 2021). "Studies have shown that downregulation of Mcl-1 through CDK7 and 2/9 inhibition facilitates the induction of apoptotic cell death in a number of different tumour types." (PMID 34344865, 2021). "Mechanistically, the reduction of both MCL‐1 and BCL‐XL was likely the result of genotoxic stress induced in tumor cells because of alpha particle‐mediated DNA damage." (PMID 33347715, 2021). "The administration of emetine decreased tumor growth by 77% with reduced amounts of EGFR and MCL1 proteins." (PMID 34203709, 2021). "Western blotting analysis revealed that tumour tissues from the LiCl group displayed higher levels of NOXA and lower levels of Mcl-1 than those from the normal saline group." (PMID 33557839, 2021). "Next, to evaluate the anti-tumor activity of MCL-1 inhibitors in KSHV+ BCBL-1 cells ex vivo, we performed soft agar colony assays in the absence or presence of MCL-1 inhibitors (AT-101 or A-1210477), followed by crystal violet staining to count colonies." (PMID 33471866, 2021). "In this context, functional BH3 profiling is an extremely useful tool to identify tumor types that depend on targetable anti-apoptotic BCL2 family members like BCL-xL and MCL-1 for their survival." (PMID 34781947, 2021). "Second, because the immunoprecipitation assay used in this study will limit the widespread testing of BAK/MCL1 complexes, better methods need to be developed to detect BAK/MCL1 complexes, especially at the level of tumor tissue." (PMID 34385422, 2021). "To examine the significance of oxidative stress on the tumor formation of DEN-injected mice, we administered N-acetyl-L-cysteine (NAC) in drinking water for 12 weeks to DEN-treated Mcl-1 KO mice from the age of 6 weeks, which was 4 weeks after DEN injection." (PMID 33564095, 2021). "Complex 14 was able to selectively inhibit MCL-1 and disrupt MCL-1/BAX and MCL-1/BAK complexes in tumor cells, inducing BAX/BAK-dependent apoptosis in tumor cells." (PMID 33883020, 2021). "According to the mechanism proposed in this study, MYC amplification triggers copy number variation resulting in amplifications of other genes, including MCL1, which cooperates with MYC in sustaining tumour growth." (PMID 34389725, 2021). "As an important tumor suppressor, FBXW7 participates in the degradation of many oncogenes, such as Myc, c-Jun, cyclin E, mTOR, Notch-1 and Mcl-1." (PMID 32296023, 2020). "As occurs in tumor cells, the reduction of FBW7 leads to increased levels of anti-apoptotic proteins p-c-Jun, MCL1 and cMYC during ehrlichial infection." (PMID 32353058, 2020). "The surveying of anti-apoptotic Bcl-2 proteins in different tumor types led to a focus on the members more frequently expressed: BCL2, Bcl-xL, and MCL1." (PMID 33396645, 2020). "The overexpression of oncogenic proteins, such as Cyclin-D1, MCL-1, C-FLIP, XIAP, MMP-9, MMP-2, uPA, and VEGF, are correlated with constitutive NF-κB activity and involved in promoting tumor progression in CRC." (PMID 32429376, 2020). "ERK1/2 promotes cell survival in BRAF- or KRAS-mutant tumor cells by increasing the expression of pro-survival BCL-2 proteins and further stabilizes the MCL-1 protein." (PMID 33308268, 2020). "In order to avoid this death-inducing signals, tumor cells are often selected for upregulation of antiapoptotic BCL-2 family members including BCL-2, BCL-xl, BCL-W, BFL-1, and MCL-1." (PMID 32190086, 2020). "Once again, while BCL-xL upregulation was observed in specific tumors in both tumor groups, the BCL-xL/MCL-1 ratio was significantly increased, both in stage I-II and in stage III-IV tumors." (PMID 32024199, 2020). "miR-15a/16 exerts tumor suppressive roles by targeting multiple oncogenes, including BCL2, TWIST1, MCL1, CCND1 and WNT3A." (PMID 32678069, 2020).